INS (insulin)
Diseases named in the same sentence as INS in open-access papers (continued):
Sharing a sentence is not in itself a finding about the gene and the disease.
diabetes (continued). "Failure of pancreatic beta cells to secrete sufficient insulin to return high blood glucose rapidly to baseline is necessary and sufficient for diabetes to occur." (PMID 35618782, 2022). "The ability to differentiate iPSC into insulin-producing pancreatic β-like cells has opened a new path for treating diabetes." (PMID 37193354, 2022). "So the affordability of insulin products in the private sector represents the majority of the patients with diabetes in Pakistan." (PMID 35431962, 2022). "With regard to smoking, taking diabetes oral medication, and insulin, only in the rural sample there was a statistically significant association, where smoking is associated with an 82% average decrease in out-of-pocket medication expenditures." (PMID 36339153, 2022). "In health and against CVD, adiponectin exerts anti-inflammatory actions in obesity, type 2 diabetes mellitus, metabolic syndrome, and atherosclerosis, increasing insulin sensitivity." (PMID 36362238, 2022). "Many people with diabetes are desperately trying to identify alternative ways to access insulin owing to its current cost." (PMID 35436214, 2022). "We focused on the doses of insulin and dextrose used, the sequence of administration, the presence of diabetes, and pre-treatment glucose concentrations." (PMID 35552566, 2022). "2.Consider prescribing shorter-acting insulin types (e.g., insulin isophane) to pregnant patients with diabetes mellitus and CKD stage 3b or higher given the extended duration of action of insulin in these patients." (PMID 36506226, 2022). "In diabetic dogs, there was little significant difference between the success of control of diabetes when compared to recombinant human NPH insulin in the same groups of dogs." (PMID 35152907, 2022). "It identified that high acquisition cost resulted in underutilisation of diabetes management technology, with only 21% of individuals with type 1 diabetes accessing insulin pumps over their lifetime." (PMID 36112608, 2022). "As a result, the muscle architecture of T1D people is adversely affected by insulin deprivation, so regular physical activity should be an integral part of diabetes treatment." (PMID 35668406, 2022). "Increased attention in studying the role of gonadal hormones in diabetes is not only due to their relation to insulin sensitivity, and glucose tolerance but also to the gender-specific nature of the prevalence of various diabetic complications." (PMID 35592207, 2022). "Little is known about body composition changes in type 2 diabetes mellitus (T2DM) patients on insulin therapy who use sodium–glucose cotransporter-2 (SGLT2) inhibitors versus dipeptidyl peptidase-4 (DPP4) inhibitors." (PMID 36224294, 2022). "A number of studies have shown that the browning of adipose tissue and the thermogenesis of brown fat affect insulin resistance and glucose metabolism, which are of great significance for the improvement of obesity and diabetes." (PMID 35462933, 2022). "Usually, dynamic physiological models are used to describe and model the glucose and insulin concentration dynamics in diabetes." (PMID 36968645, 2022). "The results of the mmLbL-INS microspheres showed that it was glucose-mediated INS release and an enhanced hypoglycemic effect for diabetes care." (PMID 36246353, 2022). "Thiazolidinediones are a drug class of PPARγ agonists currently approved for the treatment of diabetes due to their insulin-sensitizing effects, with similar effects on glycemic control between different substances of the class." (PMID 35457120, 2022). "Successful in vitro differentiation of human embryonic stem cells (hESCs) into insulin-producing cells (IPCs) raises hope for the future use of this method in the treatment of diabetes." (PMID 36232910, 2022). "Insulin is one of the major definitive effective treatments of diabetes and its effectiveness includes four critical accomplishments: initiation, adherence, persistence, and intensification." (PMID 36554673, 2022).
diabetes (continued). "CircGlis3 is involved in lipotoxicity-induced β cell disorder and the development of diabetes by suppressing insulin secretion and cell proliferation." (PMID 36386812, 2022). "The findings of the present study also suggested that monitoring of sleep duration in patients with T2D is warranted, particularly in those taking insulin, with early-onset diabetes, longer diabetes duration, poor glycemic control, and older age." (PMID 35477572, 2022). "In type 1 diabetes mellitus (T1DM), these disruptions are caused by hypoinsulinemia, but in type 2 diabetes mellitus (T2DM), they are caused by insulin resistance and decreased insulin secretion." (PMID 35802659, 2022). "The prescribed drug varies by the type of diabetes diagnosed, though insulin is the most common treatment." (PMID 36128718, 2022). "Identified pathways described various aspects of diabetes pathogenesis, including glucose and insulin signaling, regulation, and transport; natural killer cell mediated cytotoxicity; and fatty acid biosynthesis and metabolism." (PMID 36704034, 2022). "For insulin, BioEmbedS-predicted genes overlapped with 691 of the 1507 Diabetes Mellitus genes recorded in DiSGeNET (disease enrichment P=9.55×10−40), and 534 of these 691 overlapping disease genes were novel predictions (disease enrichment P=4.85×10−9)." (PMID 36000859, 2022). "MODY3 is characterized by reduced insulin secretion before the onset of diabetes and displays a distinct phenotype from type 1 and type 2 diabetes." (PMID 35328643, 2022). "It has been recognized as an acute phase reactant, and its levels increases in inflammatory and metabolic disorders such as increasing insulin levels, glucose intolerance, diabetes, and obesity." (PMID 36364861, 2022). "One hundred years have passed since pancreatic insulin extracts were first used to manage diabetes mellitus successfully in a dog for 76 days." (PMID 35152907, 2022). "In mice fed with high fat diet (HFD), HDAC11 deletion significantly decreases blood insulin levels, stabilizes blood glucose, and greatly reduces blood glucose levels after insulin challenge, thereby enhancing glucose tolerance and ameliorating diabetes." (PMID 36339432, 2022). "Diabetes is a group of metabolic diseases characterized by hyperglycemia resulting from defects in insulin action." (PMID 35269401, 2022). "Diabetes is a group of metabolic disorders characterized by chronically high levels of blood sugar due to insufficient insulin production (T1DM) or poor response of receptor cells to insulin (T2DM)." (PMID 35600580, 2022). "Training PCPs to deliver subspecialty diabetes care including management of insulin, diabetes technology, and oral adjuvant therapy via a tele-education model is effective in improving provider confidence." (PMID 36589850, 2022). "In diabetes, the serum lipoprotein concentration also increases due to the disorder of insulin-inhibiting lipoprotein production." (PMID 36499655, 2022). "Such a device would enable patients to take a more hands-off approach in their diabetes management and simplify their day-to-day insulin regimens." (PMID 36072265, 2022). "We used standard measures from fasting glucose, glucose tolerance tests, insulin, and HbA1c to evaluate precursors of diabetes." (PMID 35049608, 2022). "Iterative advances in automated (closed loop) insulin delivery have provided clinically significant improvements in glycemia, with the ultimate goal of simultaneously reducing the burden of diabetes management." (PMID 34694909, 2022). "Type 1 diabetes mellitus (T1DM) is a disease in which the autoimmune system attacks Langerhans insulin-producing cells." (PMID 36037202, 2022). "In the current study, 18.6% of patients with diabetes duration < 10 years and 16.6% of patients with diabetes duration ≥ 10 years were on insulin in addition to other antidiabetic drugs." (PMID 35794201, 2022).
diabetes (continued). "A continuous glucose monitoring system (CGMS) can monitor the blood sugar level of patients with severe diabetes to facilitate the accurate delivery of insulin to patients." (PMID 36176618, 2022). "Type 2 diabetes mellitus (T2DM) is a type of diabetes marked by elevated blood glucose levels resulting from defective insulin secretion and insulin resistance." (PMID 36159557, 2022). "The average age of onset of diabetes was 13.55 ± 8.292) years, the average age of diagnosis was 41.11 (± 16.412) years and the average time on insulin was 7.66 (± 6.704) years." (PMID 35573427, 2022). "International Society for Pediatric and Adolescent Diabetes (ISPAD) noted the importance of partial remission in the early stages of type-1 diabetes following insulin treatment initiation, known as the honeymoon phase." (PMID 35725652, 2022). "Diabetes mellitus (DM) is a group of metabolic disorders, the characteristics of which include chronic hyperglycemia owing to defects in insulin function, insulin secretion, or both." (PMID 36364178, 2022). "In a meta-analysis of trials, PUFAs significantly improved insulin secretion capacity and lowered fasting glucose levels in older individuals and those with diabetes." (PMID 35057547, 2022). "EVs released from these activated beige adipocytes contained factors that were protective against diabetes, which when administered to primary white adipocytes, increased insulin sensitivity, and insulin-stimulated glucose uptake." (PMID 35283789, 2022). "Globally, 14 million more men are diagnosed with diabetes than women; sex differences in glucose clearance, glucose-stimulate insulin secretion, and glucagon-like peptide 1 are also reported." (PMID 35883660, 2022). "Very few and heterogeneous studies, mostly excluding patients with diabetes, are available regarding the clinical effect of insulin added directly into PN bags." (PMID 36992742, 2022). "Gregory (2019) was the only paper to mention flash glucose monitoring as a tool to facilitate diabetes management for people using insulin, as this is a relatively recent technological development." (PMID 35983585, 2022). "The Opt2mise Glucose Control in Type 2 Diabetes Mellitus With Insulin Pump Therapy (OpT2mise) was the first large scale randomized trial that studied the effects of insulin pump therapy in 331 adults with T2D, including 69 subjects aged 65 years and older." (PMID 35763323, 2022). "Diabetes results from an inability of β-cells to compensate for increased demand for insulin, or from decompensation resulting from a glucotoxic environment from prolonged hyperglycemia." (PMID 35908073, 2022). "The increased expression of TBP-2 can lead to impaired insulin sensitivity and glucose-induced insulin secretion, as well as β-cell apoptosis, leading to diabetes." (PMID 35069971, 2022). "Diabetes mellitus (DM) is a chronic disorder that affects lipid, carbohydrate, and protein functions, resulting in persisting hyperglycemia, as sourced from abnormal insulin secretion, insulin action, or both." (PMID 35197753, 2022). "Insulin sensitivity; Activation of stellate cell; non-insulin-dependent diabetes mellitus; Chemotaxis of macrophages; Accumulation of fat; synthesis and concentration of triacylglycerol." (PMID 36267567, 2022). "Type 2 diabetes mellitus (T2DM) is a progressive metabolic disorder characterized by elevated circulating glucose due to glucose intolerance, caused by insufficient insulin production from the pancreas, and resistance to insulin action." (PMID 35409287, 2022). "The research and body of literature pertaining to insulin-requiring diabetes and Ramadan remain sparse." (PMID 35634376, 2022). "Type 2 diabetes mellitus is a chronic metabolic disease characterized by uncontrolled insulin secretion, hyperglycemia, and hyperlipidemia." (PMID 35845787, 2022).
diabetes (continued). "People with diabetes and their support networks have developed open-source automated insulin delivery systems to help manage their diabetes therapy, as well as to improve their quality of life and glycemic outcomes." (PMID 35357312, 2022). "These recommendations included organizational advocacy to improve insulin affordability and the availability of diabetes management resources." (PMID 36040537, 2022). "Diabetes mellitus is a disease resulting from impairment in insulin secretion, which is characterized by an increased level of blood glucose." (PMID 36013516, 2022). "Among 982 participants, 22% older persons had diabetes, 16% were taking diabetes insulin medications, and 6% taking insulin injections." (PMID 35044500, 2022). "The hormone profiling showed reduced levels of insulin, which was responsible for diabetes precipitation." (PMID 35832818, 2022). "While a series of analyses from the Diabetes Control and Complications Trial suggested that insulin intensification led to unintended weight gain, more recent analyses argue that this phenomenon is not necessarily true with current approaches." (PMID 35127949, 2022). "Insulin users had the longest median diabetes duration and the highest proportion of metastasized RC of all five study groups." (PMID 36139140, 2022). "Diabetes is a metabolic disorder that is characterized by a state of hyperglycemia, that occurs alongside dysregulations in insulin levels and in some cases, it arises concurrently to overweight and obesity." (PMID 35899107, 2022). "Among them, 2860 DIP patients were grouped according to diabetes type, glycemic status, and insulin use." (PMID 35585514, 2022). "The prevalence of diabetes mellitus (especially patients on insulin) was positively correlated with CKD severity." (PMID 35528157, 2022). "Devices that continuously monitor blood glucose levels and optimize the delivery of insulin or insulin-like drugs have been successful in treating diabetes." (PMID 35203316, 2022). "The purpose of this study was to investigate the putative protective effect of pterostilbene on the two main aspects of diabetes, namely insulin resistance and decreased insulin secretion, in mice." (PMID 36145121, 2022). "Type 1 diabetes mellitus (T1DM), or insulin-dependent diabetes mellitus, is a disorder caused by an absolute deficiency of insulin, causing persistently elevated blood glucose levels and the eventual development of diabetes mellitus." (PMID 36249783, 2022). "Agrimonia eupatoria (also called church steeples, in the Rosaceae family) is a traditional medicinal herb used to treat diabetes, as it has been shown to promote insulin secretion." (PMID 36251711, 2022). "Diabetes, a common endocrine and metabolic disease in clinical practice, generally manifests a certain defect in insulin secretion due to several factors, thereafter leading to a metabolic disorder such as hyperglycemia." (PMID 35371345, 2022). "For many years, effective and reliable oral insulin delivery strategies have been sought to treat diabetes." (PMID 36387956, 2022). "Insulin is used to treat neonatal hyperglycaemia when blood glucose concentrations are consistently high, and to treat neonatal diabetes." (PMID 36542240, 2022). "The positive effects of early insulin have convincingly been shown both in healthy individuals and diabetes patients." (PMID 36062264, 2022). "The diabetes treatments for COVID-19 patients with T2D during hospitalization were counted: 28 (25.9%) only insulin, 15 (13.9%) one or more oral medications, and 65 (60.2%) oral medications plus insulin." (PMID 35047039, 2022). "Clinical characterizations of MODY include onset of diabetes at an early age (before the age of 30), autosomal dominant inheritance pattern, impaired glucose-induced secretion of insulin, and hyperglycemia." (PMID 36573710, 2022). "After induction of diabetes, serum insulin levels in the DC group significantly decreased over three months (p < 0.001)." (PMID 35725834, 2022).
diabetes (continued). "Children whose diabetes was managed by insulin injection scored higher on eating disorder survey binge eating and T-scored RCADS separation anxiety." (PMID 36508408, 2022). "One beneficial role for SIRT1 in the context of diabetes, which requires further investigation, is the potential enhancement of insulin secretion." (PMID 36176467, 2022). "Diabetes is commonly diagnosed by measuring glucose and/or insulin after an oral glucose tolerance test or by hemoglobin A1C test." (PMID 35992116, 2022). "Diabetes occurs because of a decrease in insulin secretion by beta cells of the pancreas and poor response of insulin receptors to insulin." (PMID 35831936, 2022). "Basic diabetes skills and tasks are as important, or even more important, with closed-loop therapy than with standard insulin therapy and need to be reiterated." (PMID 32914648, 2022). "Adults with SCI (≥3 years post‐injury, C4‐L2, AIS A‐D) and insulin resistance or pre‐diabetes were randomly assigned to an 8‐week iso‐caloric LC/HP diet group (n = 11) or control group (n = 14)." (PMID 36411989, 2022). "Elliott Joslin, der Nestor der Diabetologie, schrieb in einem Mission-Statement im Jahr 1923, nachdem Insulin zunehmend weltweit verfügbar war, dass Kinder mit Typ-1-Diabetes zukünftig ein gesundes und langes Leben wie Menschen ohne Diabetes führen können." (PMID 35294561, 2022). "Xbp1 deletion in beta cells of obese ob/ob or high-fat diet-fed mice triggered diabetes and worsened glucose intolerance by disrupting insulin secretory capacity." (PMID 35316840, 2022). "Treatment with antioxidants or overproduction of antioxidant enzymes can restore equilibrium in insulin production in patients with diabetes." (PMID 36304231, 2022). "Diabetes is one of the most common chronic diseases due to inadequate (or relative) systemic endocrine insulin, which is predicted to rise to 642 million by 2040." (PMID 35564086, 2022). "According to the World Health Organization (WHO), type 2 diabetes mellitus (T2DM) is a result of the inefficient use of insulin by the body." (PMID 36428864, 2022). "Sensor accuracy was not affected by factors such as body mass index, age, type of diabetes, clinical site, insulin administration, or A1c." (PMID 35657123, 2022). "This led to a decrease in insulin content, triggering glucolipid disorders and promoting the development and progression of diabetes." (PMID 35744822, 2022). "Dedicated diabetes nurses will promote continuity of care, and they will be able to educate and counsel patients and prepare patients for insulin therapy." (PMID 35924623, 2022). "Due to the therapeutic effects of insulin on glucose metabolism, PTx can reduce diabetes-related complications, such as retinopathy, nephropathy, neuropathy, gastroparesis, and cardiovascular diseases." (PMID 36271021, 2022). "The two most common forms of diabetes are due to either a diminished production of insulin (type I diabetes, T1D) or insufficient response by the body to insulin (type II diabetes, T2D)." (PMID 35350789, 2022). "Diabetes mellitus (DM) is a metabolic disorder characterized by persistent hyperglycemia due to insulin secretion or action malfunction." (PMID 35741079, 2022). "A growing number of studies have shown that these MAMs are involved in causing dysfunction of the insulin producing β cells, resistance to insulin in the peripheral tissues, leading to type 2 diabetes mellitus." (PMID 35282429, 2022). "Damage to islet β cells leads to a rapid decrease in insulin secretion and a significant increase in blood sugar, showing the appearance of diabetes." (PMID 35929595, 2022). "In contrast, type 2 diabetes mellitus (T2D) is characterized by the presence of IR, which typically results in a compensatory increase in endogenous insulin production, subsequently followed by ß-cell failure." (PMID 36551851, 2022). "The insulin subjected to the first patient with diabetes was the unpurified extract of an animal’s pancreas." (PMID 35723344, 2022).